KMT2C (lysine methyltransferase 2C)
Diseases named in the same sentence as KMT2C in open-access papers (continued):
Sharing a sentence is not in itself a finding about the gene and the disease.
cancer (227 papers, 2008 to 2026). A tumor composed of atypical neoplastic, often pleomorphic cells that invade other tissues. "Another KMT2 family member frequently mutated in cancer is KMT2C, which regulates enhancer activity in normal cells through methylation." (PMID 38791111, 2024). "There is therefore sufficient evidence to conclude that this microdeletion explains the individual’s ID and there is limited evidence to suggest that haploinsufficiency of KMT2C is cancer predisposing." (PMID 39095811, 2024). "In other cancers, KMT2C has been implicated in the therapeutic response to DNA damaging factors or inhibitors of DNA repair proteins." (PMID 36933062, 2023). "In humans, studies have demonstrated a strong association between mutations in KMT2C and carcinogenesis, highlighting the connection between epigenetic regulation and the development of cancer." (PMID 37538398, 2023). "According to the database, among the KMT2A-D proteins, KMT2C is the most frequently mutated (~ 4 050 cases of cancer patients), followed by KMT2D (~ 2 600 cases), KMT2A (~ 1 580 cases), and finally KMT2B (~ 1 250 cases)." (PMID 36598580, 2023). "KMT2C is mainly involved in enhancer-associated H3K4me1, and is also one of the top mutated genes in cancer (6.6% in pan-cancer)." (PMID 37415738, 2023). "As one of the critical epigenetic regulators, KMT2C frequently mutates in diverse cancers and is a crucial biomarker in detecting the occurrence or progression of diverse cancers." (PMID 35847355, 2022). "We found that ECs harbored not only known mutations in driver genes, such as ARID1A, CTNNB1, PIK3CA, and PTEN, but also novel mutations in cancer-related genes, such as KMT2C and PRKAR1A." (PMID 35626111, 2022). "Frequent truncation mutations of the histone lysine N-methyltransferase KMT2C have been detected by whole exome sequencing studies in various cancers, including malignancies of the prostate." (PMID 35354467, 2022). "Reportedly, KMT2D collaborates with the SWI/SNF complex to promote cell type-specific enhancer activation, and cancer cells with KMT2C deficiency have higher endogenous DNA damage and genomic instability." (PMID 36371186, 2022). "A summary of more than 33,000 cases conducted by the National Cancer Institute Genomic Data Commons (GDC) has revealed that lysine methyltransferase 2C (KMT2C) is the seventh most frequently mutated gene in cancer." (PMID 35945529, 2022). "Mutations in cancer-related genes (KMT2C, NOTCH2, PRKAR1A, SDHA, and USP6) and genes related to EC (ARID1A, CTNNB1, PIK3CA, and PTEN) were identified with high frequencies among the three samples." (PMID 35626111, 2022). "Whole exome sequencing studies of various human cancers have identified frequent somatic mutations in the gene encoding the histone-methyltransferase KMT2C." (PMID 35354467, 2022). "As an important epigenetic regulator, histone lysine methyltransferase 2C (KMT2C) is frequently mutated in a variety of human cancers and is considered to be essential in the development of many cancers." (PMID 33968723, 2021). "The histone 3 lysine 4 (H3K4) monomethylase KMT2C is mutated across several cancer types; however, the effects of mutations on epigenome organization, gene expression, and cell growth are not clear." (PMID 32471474, 2020). "The H3K4 monomethylase KMT2C is a frequent target of mutations in CRC and other cancer types, and studies have demonstrated different effects of different mutations on KMT2C function, suggesting the need for further investigation of KMT2C in tumorigenesis." (PMID 32471474, 2020). "KMT2C mutates frequently and is considered crucial for the occurrence and development of numerous cancers." (PMID 32010606, 2019). "KMT2C is frequently mutated in a broad spectrum of cancers and it has been related to tumorigenesis." (PMID 29113313, 2017). "According to the latest updated ICGC data, KMT2C is the sixth most frequently affected gene across 43 distinct cancer genomes when only variants with severe impact are considered." (PMID 27195705, 2016).
cancer (continued). "KMT2C is a member of the lysine methyltransferase family, and mutations in this gene are associated with the progression, metastasis, and drug resistance of various cancer types." (PMID 40723577, 2025). "Other recurrently mutated cancer genes included chromatin modifiers KMT2C (n=2) and BCOR (n=2)." (PMID 38978571, 2024). "Previous studies indicate that mutations in FAT4 may contribute to the development of 24 types of cancers, while mutations in KMT2C may lead to 32 types of cancers." (PMID 39541191, 2024). "Thus, we focus on the structure of KMT2C as well as the cancers associated with KMT2C and its mechanism of action in cancer, and discuss the related challenges in the hope of providing possible application value." (PMID 39165358, 2024). "Furthermore, ASCC exhibited somatic missense mutations in cancer driver genes, with KMT2C, PIK3CA, and EP300 being the most mutated genes, in agreement with previous reports." (PMID 39024554, 2024). "KMT2C mutations have been reported to correlate with patient prognosis in many cancer types." (PMID 37415738, 2023). "Cancer Genome Atlas (TCGA) pan-cancer analysis suggested that the association of KMT2C/BCOR/KDM5C mutations with ICB response observed here might not result from DNA repair defects." (PMID 35681795, 2022). "In contrast to previously published data of the mutational pattern of KMT2C in different human cancers, KMT2C mutations in the analysed PCa dataset were distributed along the gene with no apparent mutational hotspot in keeping with the types of mutations commonly observed in tumour suppressor genes." (PMID 35354467, 2022). "Recurrent somatic mutations in chromatin remodeling-related genes have been detected with high frequency in human cancers, and three of them, including KMT2D, ARID1A and KMT2C, were the third, fifth and seventh-most commonly mutated cancer genes in a pan-cancer cohort containing around 33,000 cases." (PMID 35681795, 2022). "Furthermore, analysis of gene functions showed similarities between the differentially expressed gene sets enriched in RKO and HCT116-derived clones, identifying cell signaling pathways with well-known association to cancer as affected by KMT2C expression." (PMID 32471474, 2020). "In the unclassified subgroup, apart from previously reported mutations in epigenetic regulators in multiple cancers, including KMT2C, KMT2D, KMT2B, PRDM2, NCOR2, KAT6B, and EP300, in this cohort, we also found new recurrent mutations in epigenetic regulators, including CREBBP and PRDM16." (PMID 30950204, 2019). "Distant organ metastases are still the leading cause of cancer-related deaths, and the KMT2C gene, a high-frequency mutated gene common to both primary and metastatic foci of lung cancer, may provide a potential biomarker for immune checkpoint blockade in LUAD with metastases to different organs." (PMID 39165358, 2024). "This, opens up the possibility that KMT2C-associated cancers may be targeted by PARP1/2 inhibitors." (PMID 33381456, 2020). "The cancer-associated genes PTEN (7%), KMT2C (7%), KMT2D (7%), RB1 (6%), and CREBBP (4%), were again among the 15 most frequently mutated and at similar frequencies as observed in CALGB 40603." (PMID 40057511, 2025). "For HPV-associated SNSCC with matched normal DNA the most frequently mutated COSMIC cancer driver genes included KMT2D (4/12 patients, 33%), FGFR3 and KMT2C (3/12 patients, 25%), GOLGA5, TET1, and ARID1B (2/12 patients, 16.7%)." (PMID 40500270, 2025). "When combined with deletion of Kmt2c and/or Kmt2d, the bladder urothelium exhibited dysplasia that progressed to nuclear pleomorphism and abnormal mitoses fulfilling the criteria of carcinoma in situ (CIS) in some mice." (PMID 39806204, 2025).
cancer (continued). "Other notable mutated cancer-related genes include PIK3CA (7%), CREBBP (6%), KMT2C (6%), KMT2D (6%), RB1 (5%), PTEN (5%), and FAT1 (5%), all of which are reported as “Tier 1” cancer-related gene mutations in the COSMIC Cancer Gene Census21." (PMID 40057511, 2025). "The cancer-associated transcripts including NF1, ATM, MUC16, and KMT2C, were found at higher mRNA levels with ExCy." (PMID 40598203, 2025). "Alterations in KMT2C can disrupt this regulation, leading to abnormal expression of genes involved in cell growth, division, and differentiation, which can contribute to cancer development." (PMID 39769419, 2024). "Several studies found that cancers harboring mutations in the components of the COMPASS-like complex, including KDM6A, KMT2C, and KMT2D, were associated with poor differentiation and aggressive behavior." (PMID 38791111, 2024). "KMT2C was found to be aberrantly expressed in cell lines and tumor tissues of many tumor patients, suggesting that KMT2C is involved in many cancer-related signaling pathways." (PMID 39165358, 2024). "According to the list of the top 10 most frequently mutated genes, MUC4, MUC16, KMT2C, and PREX2 were annotated as cancer driver genes." (PMID 39338204, 2024). "Conversely, ctDNA from both Patients 6 and 7 had mutations in two known cancer critical genes each (BRCA1 and IDH1, and ERG and KMT2C, respectively)." (PMID 35880692, 2023). "Recurrent mutations in the genes encoding MLL3 (KMT2C) and MLL4 (KMT2D) are frequently found in a broad spectrum of cancers, and some are thought to behave as oncogenic drivers." (PMID 37252797, 2023). "Well‐known cancer critical genes like BRCA1, IDH1, ERG, KMT2C, MSH6 and PALB2 were among the mutated genes in the metastatic samples." (PMID 35880692, 2023). "We presented a comprehensive characterization of KMT2A, KMT2B, KMT2C, and KMT2D pathogenic variation in a large cancer‐free adult population, with ancestry‐ and sex‐specific frequencies." (PMID 36479909, 2023). "Mutations in epigenetic modifier enzymes KMT2B, KMT2C, KMT2D, and ARID1A were more prevalent in MSI cancers, where the majority possessed KMT2B and KMT2D mutations and over one-third had KMT2C and ARID1A mutations (χ2 test p = 0.001)." (PMID 37998722, 2023). "Genotype–phenotype correlations have been established between KMT2A (11q23.3), KMT2B (19q13.12), KMT2C (7q36.1), and KMT2D (12q13.12) somatic variants and different cancer types." (PMID 36479909, 2023). "KMT2C (MML3) and KMT2D (MLL4) are among the most frequently mutated genes in cancer and the mutations inactivate function." (PMID 35406676, 2022). "Although mutations in the SET domain of KMT2C and KMT2D are common in cancer (>25% of mutations), mutations are also found in other domains, including the PHD domains." (PMID 35406676, 2022). "Of the six Compass complexes that can methylate H3K4, KMT2A/MLL1, KMT2C, and KMT2D (MLL3 and 4) have been most widely implicated in cancer." (PMID 35406676, 2022).
cancer (continued). "Previous studies have shown correlations between expression levels of KMT2C and cancer progression, while others have instead highlighted the importance of genetic alterations affecting protein function." (PMID 35354467, 2022). "Of these, several are found in genes involved in DNA damage response and double-strand DNA repair mechanisms, including MCL1, ATR, KMT2C, and CBLC, indicating genomic instability and cancer predisposition." (PMID 34299215, 2021). "We identified 14 cancer driver genes, including the most frequently altered KMT2C (100%), KNL1 (100%), NCOR2 (100%), and CCDC6 (93%) genes." (PMID 34245124, 2021). "Similar to MLL4, the related histone methyltransferase, MLL3 (KMT2C), also catalyzes H3K4me1and is frequently mutated in numerous human cancers, including SCCs." (PMID 34890228, 2021). "The NGS analyses identified mutations in eight cancer associated genes: ESR1, MECOM, JAK3, KMT2C, CTNNB1, CALR, NCOR1 and AMER." (PMID 34209696, 2021). "KMT2C and KMT2D histone lysine methyltransferases are among the most frequently mutated genes across a variety of cancer types." (PMID 33381456, 2020). "To further confirm the role of KMT2C in the cancer stem cells and Taxol resistance, we respectively overexpressed XIST in the SKOV3-KD group, as well as knocked down XIST in the TOV21G-OE group, labelled as SK-KD + 2C-OE and T-OE + 2C-KD, respectively." (PMID 32943985, 2020). "Recent studies have shown that the role of KMT2C/D gene is generally known to perform enhancer regulation by deposition of H3K4me1 in normal cells and a transcription regulator in cancer." (PMID 32718341, 2020). "We report for the first time that the epigenetic regulator KMT2C is significantly downregulated in many different types of cancer." (PMID 30665945, 2019). "Additional cancers that have recently been found to be driven by an aberrant KMT2D/KMT2C pathway, with frequencies ranging from 5% to 40%, include renal, prostate, bladder, gastric, hepatic and lung cancer." (PMID 24240169, 2013). "Apart from the genetic evidence, the role of KMT2C in tumorigenesis and in cancer progression was first suggested by a KMT2C knockout mouse model that developed ureter epithelial tumors." (PMID 24240169, 2013). "Advancements in cancer exome sequencing studies have supported somatic KMT2C haploinsufficiency in acute myeloid leukemia, pancreatic ductal carcinoma, bile duct carcinoma, cutaneous squamous cell carcinoma, gastric adenocarcinoma, and hepatocellular carcinoma." (PMID 36479909, 2023). "UTX (KDM6A), MLL3 (KMT2C), and MLL4 (KMT2D), the core catalytic components of the COMPASS-like complex, are all considered tumor suppressors, with frequent loss-of-function genomic alterations found in a broad spectrum of human cancers." (PMID 37261974, 2023).
cancer (continued). "A commonly mutated gene in human PCa is KMT2C, but mice with the loss of Kmt2c alone do not display a clear cancer-related phenotype." (PMID 37686488, 2023). "In this regard, MLL2/KMT2D and MLL3/KMT2C complexes are required to maintain H3K4me1 levels in enhancers, thereby modulating enhancer activities during development and in cancer." (PMID 36968588, 2023). "The expression levels of KMT2A and KMT2C, as well as KMT2C and KMT2H, were the most associated across all 33 cancer types among the eight KMT2 gene members, indicating that they may share certain activities." (PMID 35058979, 2022). "LRP1B and KMT2C were subclonal in two primary cancers (UCEC and BRCA, UCEC and LUNG, respectively)." (PMID 36497297, 2022). "In the TCGA study on muscle-invasive UC, about 90% of the cancers carried one or more mutations in KDM6A (encoding histone demethylase UTX), KMT2C, KMT2D (encoding histone methyltransferases MLL2 and MLL3), CREBBP, EP300 (histone acetyltransferases), and ARID1A (a SWI/SNF component)." (PMID 34885146, 2021). "Furthermore, a recent study demonstrated that downregulation of KMT2C compromised the homologous recombination‐mediated double‐strand break DNA repair function in several cancer types, including NSCLC." (PMID 33655698, 2021). "In addition, this study found that KMT2C overexpression inhibited XIST silencing-induced cancer stem cell and paclitaxel resistance in vitro." (PMID 32943985, 2020). "Among ERGs that could be classified as tumor suppressors, KMT2D, KMT2C, ARID1A, ATRX, CREBBP, and PBRM1 were frequently mutated in many cancer types, whereas oncogenic ERGs were each mutated in specific cancer types, mainly IDH1 in LGG and DNMT3A in LAML." (PMID 32963031, 2020). "The genes encoding KMT2C (MLL3) and KMT2D (MLL4) are among the most frequently mutated in cancer." (PMID 32471474, 2020). "Overexpression of KMT2C impaired XIST lost-induced cancer stem cells and Taxol resistance in vitro." (PMID 32943985, 2020). "Though the biological role of MLL3 histone methyltransferase in carcinogenesis remains unknown, LOF mutations and downregulation of this gene in cancers suggest that KMT2C may act as tumor suppressor gene." (PMID 30828495, 2019). "We thus speculate that loss‐of‐function mutations in combination with progressively reduced gene expression due to promoter methylation limit KMT2C activity in cancer cells." (PMID 30665945, 2019). "Moreover, differences in enhancers’ status defined by H3K4me1 profile, which is regulated by MLL2/KMT2D and MLL3/KMT2C, can be found between normal and cancer cells." (PMID 29483845, 2018). "Indeed, in recent years, several other studies have been demonstrating that MLL2/KMT2D and MLL3/KMT2C genes are involved in a multitude of cancers." (PMID 29483845, 2018). "Therefore, cancer cells with low KMT2C activity may be effectively treated with PARP inhibitors that have synthetic lethal effects." (PMID 33159839, 2021). "Therefore, the overexpression of KMT2A and KMT2C could maintain the chromatin active signature and facilitate the maintenance of stemness in cancer stem cells." (PMID 29728583, 2018). "Finally, KMT2C catalyses the monomethylation of H3K4 in collaboration with hormone receptors and transcription factors involved in developmental signalling; it is one of the histone modifiers previously implicated in some cancer types." (PMID 29113313, 2017).